GRIP2 (glutamate receptor interacting protein 2)
Description:
May play a role as a localized scaffold for the assembly of a multiprotein signaling complex and as mediator of the trafficking of its binding partners at specific subcellular location in neurons.
Synonyms: KIAA1719; ABP
Tractability: Antibody: its Gene Ontology location is reachable by antibodies, with high confidence; UniProt places it where antibodies can reach, with medium confidence.
Gene: Protein-coding gene on chromosome 3 (14,489,107 to 14,556,075, reverse strand). Ensembl gene ENSG00000144596.
Subcellular location: Cytoplasm; Membrane
Subcellular location (Human Protein Atlas): Cytosol
Pathways (Reactome):
Neuronal System: Trafficking of GluR2-containing AMPA receptors
Gene Ontology:
Molecular function: protein binding
Biological process: neurotransmitter receptor transport, endosome to postsynaptic membrane
Cellular component: cytosol; plasma membrane; cytoplasm; glutamatergic synapse; membrane
Genetic constraint (gnomAD): Loss-of-function variants: 55 observed, 85.76 expected, observed/expected ratio (o/e) 0.64, 90% interval 0.51 to 0.8. The upper end of that interval is the gene's LOEUF score, 0.8, which puts it in group 3 of 6, group 1 being the genes least tolerant of losing a copy. Missense variants: 1,223 observed, 1,317.7 expected, observed/expected ratio (o/e) 0.93, 90% interval 0.88 to 0.97. Synonymous variants: 567 observed, 547.78 expected, observed/expected ratio (o/e) 1.04, 90% interval 0.96 to 1.11.
Homologues: Orthologues: chimpanzee GRIP2 (99% identical), macaque GRIP2 (98% identical), dog GRIP2 (93% identical), pig GRIP2 (91% identical), mouse Grip2 (88% identical), rat Grip2 (87% identical), rabbit GRIP2 (85% identical), guinea pig GRIP2 (76% identical), tropical clawed frog grip2 (70% identical), zebrafish grip2b (67% identical), zebrafish grip2a (38% identical). Paralogues in human: GRIP1 (62% identical), MAGI1 (20% identical), MAGI2 (19% identical), MAGI3 (19% identical), MAGIX (6% identical), SAV1 (5% identical).
Diseases named in the same sentence as GRIP2 in open-access papers:
GRIP2 is named in the same sentence as 9 diseases in open-access papers, as found by Europe PMC text mining. Sharing a sentence is not in itself a finding about the gene and the disease. The quoted sentences say what the papers report.
Alzheimer disease (2 papers, 2012). A progressive, neurodegenerative disease characterized by loss of function and death of nerve cells in several areas of the brain leading to loss of cognitive function such as memory and language. "Grip encodes a glutamate receptor binding protein involved in synapse organization and its human homolog, GRIP2, has been implicated in Alzheimer's disease." (PMID 22496853, 2012). "GRIP2, the human homolog of Grip, has been implicated in Alzheimer's disease." (PMID 22715409, 2012).
breast carcinoma (1 paper, 2021). "Variant rs1106333 on chromosome 3, whose nearest gene is GRIP2, was associated with risk of dying of breast cancer in the subgroup of patients with an ER− tumor who received chemotherapy (HR [95% CI] 1.68 [1.39,2.03], P = 5.6E−08, BFDP = 0.12 per A allele)." (PMID 34407845, 2021). "PanCanGTL revealed the presence of a cis-eQTL linking variant rs1106333 with GRIP2 expression in prostate adenocarcinoma but not in breast cancer." (PMID 34407845, 2021).
tumor (3 papers, 2015 to 2025). "Thus, GRIP2 may regulate both tumor signaling pathways and immune cell function, making it a promising therapeutic target." (PMID 40575157, 2025).
cancer (1 paper, 2025). A tumor composed of atypical neoplastic, often pleomorphic cells that invade other tissues. "Given the frequent dysregulation of signaling pathways in cancer cells, GRIP2 may influence HNSCC progression by modulating key tumorigenic pathways." (PMID 40575157, 2025).
GRIP2 also shares sentences with these, for which no sentence is quoted: schizophrenia (2 papers); endothelial dysfunction (1); head and neck tumors (1); prostate adenocarcinoma (1); psychosis (1).